DCN (decorin)
Diseases named in the same sentence as DCN in open-access papers (continued):
Sharing a sentence is not in itself a finding about the gene and the disease.
COVID-19 (continued). "Of interest, DCN and TNFRSF12A were distinctly elevated in severe COVID-19, separating severe disease from moderate, while MCP-3 and HGF were found to increment with disease severity." (PMID 39767799, 2024). "We found the combination of the following factors to be of most interest to follow up on in a larger cohort of post-COVID-19 patients: CXCL13, DCN, HGF, MCP-3 and TNFRSF12A." (PMID 39767799, 2024). "The fibronectin (p < 0.0001) and the versican (p = 0.044) densities were increased in the COVID-19 cases compared to the non-COVID-19, whereas the decorin density was decreased in the COVID-19 cases compared to the non-COVID-19 (p = 0.033)." (PMID 37964271, 2023). "All assessed ECM components, collagen (p < 0.0001; η2 = 0.38), fibronectin (p < 0.0001; η2 = 0.34), versican (p = 0.013; η2 = 0.15), decorin (p = 0.028; η2 = 0.12), and TGF-β (p = 0.018; η2 = 0.14), had their expression influenced by COVID-19, except the elastic fibres (p = 0.271; η2 = 0.03)." (PMID 37964271, 2023). "We observed that COVID-19 cases presented significant increased deposition of collagen, fibronectin, versican, and TGF-β, and decreased decorin density when compared to non-COVID-19 cases of similar MV duration." (PMID 37964271, 2023).
diabetic cardiomyopathy (6 papers, 2017 to 2025). Diabetic cardiomyopathy is a disorder of the heart muscle in people with diabetes. "Overexpression of decorin is reported to ameliorate diabetic cardiomyopathy and cardiac function in rats." (PMID 32231160, 2020). "Overexpression of decorin ameliorated diabetic cardiomyopathy and promoted angiogenesis through the IGF1R-Akt-VEGF signaling pathway in endothelial cells in vivo and in vitro." (PMID 32731559, 2020). "In conclusion, overexpression of decorin ameliorated diabetic cardiomyopathy and promoted angiogenesis through the IGF1R-AKT-VEGF signaling pathway in vivo and in vitro." (PMID 28290552, 2017). "Overexpression of decorin ameliorates diabetic cardiomyopathy by promoting angiogenesis." (PMID 31569732, 2019). "Here, we investigate whether overexpression of decorin ameliorates diabetic cardiomyopathy and its effects on angiogenesis in vivo and in vitro." (PMID 28290552, 2017).
glomerulonephritis (6 papers, 2011 to 2023). A renal disorder characterized by damage in the glomeruli. "The injection of decorin hampered the TGF-β-mediated accumulation of extracellular matrix components in a rat model of glomerulonephritis." (PMID 37250906, 2023). "In an experimental rat model of glomerulonephritis, administration of decorin suppressed deposition of fibronectin in glomeruli and prevented development of proteinuria." (PMID 36558936, 2022). "DCN administration has been advocated as a potential antagonist against nephropathies because of the relative deficiency of DCN and relative excess of TGF-β1 existing in glomerulonephritis." (PMID 22279542, 2012). "Decorin (DCN), a leucine-rich proteoglycan secreted by glomerular mesangial cells (MC), is a promising anti-fibrotic agent for the treatment of glomerulonephritis." (PMID 22876812, 2012). "In a model of anti-Thy-1-initiated glomerulonephritis, injections with decorin suppressed the TGF-β activity." (PMID 21494642, 2011). "Using the hemagglutinating virus of Japan; Sendao virus (HVJ)-liposome method to transfer a DCN plasmid vector into rat skeletal muscle, Isaka and colleagues found increased amounts of DCN protein in skeletal muscle and in kidney with a marked therapeutic effect on rat glomerulonephritis." (PMID 22876812, 2012). "Therefore, DCN is a promising anti-fibrotic agent for the treatment of glomerulonephritis." (PMID 22876812, 2012). "Additionally, transfer of the decorin gene into skeletal muscle increased the amount of decorin in kidney, reduced TGF-β1 expression and ECM accumulation in kidney and attenuated proteinuria via ligand trapping in a rat model of glomerulonephritis." (PMID 36558936, 2022). "Since DCN is an important antagonizing factor for glomeruli inflammation, it is suggestion that OTUB1 may be another novel regulator involved in the pathogenesis of glomerulonephritis." (PMID 22279542, 2012).
Hyperglycemia (6 papers, 2017 to 2023). An increased concentration of glucose in the blood. "In conclusion, we found that decorin plays a causal role in protecting against diet-induced hyperglycemia." (PMID 30874564, 2019). "Collectively, these findings highlight how hyperglycemia associated with T2DM can perturb TGF-β1 and decorin secretion by MSCs and macrophages, thereby potentially influencing TGF-β1 bioavailability and signaling during bone repair." (PMID 39916897, 2023). "This study showed that decorin regulates glucose levels, primarily affecting glucose metabolism by protecting the body from potential postprandial hyperglycemia." (PMID 38136166, 2023). "In conclusion, aqueous humor decorin concentrations were found elevated in DR subjects, possibly due to a compensatory response to the retinal microvascular changes during hyperglycemia." (PMID 34947953, 2021). "They concluded that decorin may play an important role by protecting against diet-induced hyperglycemia." (PMID 38136166, 2023). "Decorin protects against the development of hyperglycemia, but may also contribute to proinflammatory processes." (PMID 38136166, 2023). "Moreover, overexpression of decorin protected endothelial function from hyperglycemia and promoted angiogenesis through IGF1R/AKT/AP-1/VEGF signaling, suggesting that decorin could be a new therapeutic strategy for patients suffering from DCM." (PMID 28290552, 2017).
Marfan syndrome (6 papers, 2009 to 2020). A disorder of the connective tissue. "Studies have shown that an enhancement in TGF-β levels occurs in Marfan syndrome, causing decorin levels to decrease through high and low affinity binding of the growth factor to the decorin core protein." (PMID 32173378, 2020). "Among human aneurysmal diseases, deficient decorin expression has been associated with lethal forms of Marfan’s syndrome and aortic dissection." (PMID 25781946, 2015). "However, deficiencies in mRNA synthesis of decorin and reduced expression have also previously been reported to occur in neonatal Marfan syndrome with abnormalities in the fibrillin gene." (PMID 32173378, 2020). "We conclude that the downregulation of fibulin-1 and/or of decorin in AAD patients could be an alternative molecular mechanism—opposed to a mutation in fibrillin-1 as seen in patients suffering from Marfan syndrome—leading to the same or similar phenotype." (PMID 19652764, 2009). "However, whether the loss of decorin could further contribute to the pathogenesis of Marfan syndrome remains to be established." (PMID 32903857, 2020). "Decorin expression has been shown to be significantly decreased in the corneas of a mouse model of Marfan syndrome and fibroblasts from a patient with Marfan syndrome." (PMID 32903857, 2020). "Marfan Syndrome-associated MVP is accompanied by myxomatous changes in the ECM as indicated by an abnormal accumulation of proteoglycans, largely decorin, versican and lumican and changes in collagen fibers including increased expression." (PMID 32824919, 2020). "Decorin is thought to regulate Transforming growth factor beta (TGFB) bioavailability and mutations in this gene have been linked to Marfan syndrome." (PMID 23935926, 2013).
preeclampsia (6 papers, 2015 to 2025). Preeclampsia is a hypertensive disorder of pregnancy that is characterized by new-onset hypertension with proteinuria presenting after 20 weeks of gestation, and depending on mild or severe forms may initially present with severe headache, visual disturbances, and hyperreflexia. "Previous studies have shown that DCN overproduction by decidual cells is associated with preeclampsia by reducing EVT migratory and invasive capacity, which contributes to insufficient conversion of maternal spiral arteries 35-37." (PMID 36438479, 2022). "Decorin, a leucine-rich proteoglycan restrains trophoblast proliferation, migration/invasiveness and endovascular differentiation, and local decorin overproduction is associated with preeclampsia (PE)." (PMID 29895842, 2018). "It was reported that decidual DCN expression was increased in preeclampsia (PE) patients, and peripheral levels of both DCN and TNF-α were elevated in PE patients before the appearance of clinical signs, serving as predictive biomarkers for PE." (PMID 39508749, 2025). "In this study, serum PLGF, DCN, LDH, UA levels and pre-pregnancy BMI had a combined diagnostic curve area under the curve of 0.952 for preeclampsia, with a sensitivity of 0.901 and a specificity of 0.913, which had a good clinical diagnostic value compared with a single indicator." (PMID 38260145, 2023). "Furthermore, DCN was shown to be selectively over-produced by thedecidua in preeclampsia (PE) subjects and elevated in the second trimester maternal plasma in PE, before the appearance of clinical signs, presenting as a predictive biomarker for PE." (PMID 36299488, 2022). "Thus, we suggested that the contribution of decorin to the modulation of trophoblast cells might have implications for the pathogenesis of preeclampsia." (PMID 26357650, 2015).
prostate tumor (6 papers, 2011 to 2020). "We subsequently analyzed publicly available RNA-seq datasets from human prostate tumors for associations between MEIS- and DCN-regulated pathways." (PMID 32553107, 2020). "In prostate tumor tissues, a marked attenuation of total decorin and lumican expression was evident, whereas syndecan-1 and glypican-1 expression was increased in tumor stroma and attenuated in tumor epithelial cells." (PMID 32847060, 2020). "In parallel, TGFBR3 (also known as betaglycan) significantly increased with MEIS1 expression (fold-change = 1.67, FDR = 4.13×10−4) and has been shown to inhibit TGFβ signaling and decrease prostate tumor growth and progression in a manner similar to DCN." (PMID 32553107, 2020). "In prostate tumours, complex changes in proteoglycans occur, with a common trend towards decrease of decorin and lumican expressions, and increase an overall expression of syndecan-1 and glypican-1, shifted from the epithelial cells to tumour stroma." (PMID 23691363, 2013). "In addition, decorin is known to suppress prostate tumor growth through inhibition of epidermal growth factor and androgen receptor pathways." (PMID 32155897, 2020). "In this study, expression of cell surface and stromal proteoglycans (glypican-1, perlecan, syndecan-1, aggrecan, versican, NG2, brevican, decorin, and lumican) in normal tissue and prostate tumours was determined by RT-PCR analysis and immunostaining with core protein- and GAG-specific antibodies." (PMID 23691363, 2013). "As a result, expression patterns for main proteoglycans in prostate tumours were highly individual with an ubiquitous expression for versican and tendency for the decreased decorin and lumican expressions and increased syndecan-1 and glypican-1 expressions in tumour tissues." (PMID 23691363, 2013). "Hence, Decorin as main contributor to acidification of the microenvironment appears unlikely in PCa, as it appears less abundant in the prostate tumour stroma." (PMID 22880013, 2012). "Our results outlined a tendency for the decreased decorin expression in prostate tumours; however, a significant individual variation of decorin mRNA levels in different prostate tumours could explain the discrepancy of the experimental data from different sources." (PMID 23691363, 2013). "Fourth, previous analyses of MEIShigh vs. MEISlow prostate tumors and metastases did not prioritize proteoglycans or DCN." (PMID 32553107, 2020). "Whereas the versican expression level was relatively similar both in normal and malignant prostate tissues (35–40% of increase for versican expression was not considered as significant), decorin and lumican expressions trend towards to be decreased in prostate tumours up to 2-fold." (PMID 23691363, 2013).
renal fibrosis (6 papers, 2015 to 2024). A final common manifestation of a wide variety of chronic kidney diseases characterized by glomerulosclerosis and tubulointerstitial fibrosis. "In conclusion, highly expressed DCN mitigated renal fibrosis and thus delayed renal failure as well as mitigating the abnormal lipid metabolism of the chronic renal failure." (PMID 25574240, 2015). "Among the LLC1-derived nephrotoxic secretory proteins, ANGPL2, BMP-1, DCN, FN1, and MCP-1 have been shown to contribute to TGF-β signaling-dependent renal fibrosis." (PMID 33260558, 2020). "Blockade of TGF-β1 by neutralizing antibodies or gene silencing, decorin have demonstrated to reduce ECM production and ameliorate renal fibrosis in both in vitro and in vivo studies, whereas overexpression of TGF-β1 in mouse liver develop progressive liver and renal fibrosis." (PMID 25954203, 2015). "Indeed, DCN increases MMP-2 and MMP-9 levels, reduces extracellular matrix deposition, and attenuates fibrotic changes in animal models of many pathological conditions, including proliferative vitreoretinopathy, renal fibrosis, and spinal cord injury." (PMID 33918979, 2021).
Cirrhosis (5 papers, 2020 to 2025). A chronic disorder of the liver in which liver tissue becomes scarred and is partially replaced by regenerative nodules and fibrotic tissue resulting in loss of liver function. "A similar effect due to the presence of this proteoglycan was reported in liver fibrosis/cirrhosis, where decorin is believed to “refrain” the pro-fibrogenic activity of TGFβ." (PMID 35454809, 2022). "Decorin was found to be produced by HSCs under TGFβ1 stimulus and appears histologically coexpressed and colocalized with this cytokine in a spectrum of liver diseases, including chronic hepatitis, fibrosis, and cirrhosis." (PMID 35454809, 2022). "DCN/SMA ratio gradually decreases from very early to advanced HCC, while it is overexpressed in cirrhosis." (PMID 32477937, 2020).
emphysema (5 papers, 2006 to 2023). "Decreased decorin and biglycan expressions have also been shown in peribronchiolar areas in patients with severe pulmonary emphysema." (PMID 23406566, 2013). "However, decorin synthesis has been shown to be decreased in distal fibroblasts from patients with severe emphysema and decorin gene expression has also been shown to be decreased in centrally-derived lung fibroblasts from patients with severe COPD." (PMID 23406566, 2013). "Similarly, in severe emphysema, decorin expression is reduced to possibly aggravate the disease." (PMID 37932771, 2023).
glaucoma (5 papers, 2017 to 2024). Increased pressure in the eyeball due to obstruction of the outflow of aqueous humor. "Previous studies have shown that decorin expression is associated with lower IOP in a rat model of glaucoma and decorin-deficient mice exhibited a higher IOP." (PMID 38394161, 2024). "After glaucoma filtration treatments, the subconjuncti-val injection of decorin in rabbits showed markedly reduced conjunctival scarring and maintained lower IOP levels." (PMID 36611867, 2022). "We know of publications that draw important mechanistic conclusions on the influence of decorin on the control of sensory neuron growth, wound-healing in glaucoma, prevention of the development of vitreoretinopathy and susceptibility to malaria." (PMID 27994047, 2017). "Altered decorin expression is also associated with several fibrotic eye diseases, including congenital stromal dystrophy of the cornea, corneal wound healing, PCO, glaucoma, and PVR." (PMID 36611867, 2022). "The treatment of decorin may attenuate the remodeling process in the ON head observed during the progression of glaucoma and may reduce IOP." (PMID 36611867, 2022). "Nevertheless, we strongly believe that all these results make DCN an interesting candidate for future treatments of glaucoma due to its ability to reduce expression and synthesis as well as activity of TGF-β and CTGF/CCN2 in human and murine astrocytes of the ON and ONH." (PMID 34299278, 2021). "Thus, we propose that DCN could attenuate the remodeling process in the ONH occurring during the pathogenesis of glaucoma." (PMID 34299278, 2021). "The increased amounts of these growth factors would result in a vicious circle by the downregulation of the endogenous inhibitor DCN, resulting in a fortified remodeling of the ONH in glaucoma." (PMID 34299278, 2021). "The aqueous level of decorin was found to be decreased in eyes with glaucoma compared with non-glaucomatous eyes." (PMID 36611867, 2022). "Other studies have found vitreous concentrations of decorin to decline with age, irrespective of glaucoma or ocular hypertension in the eye." (PMID 34947953, 2021). "Thus, through the protein interaction networks of TGF-β and FGF2 that induce ECM remodeling, decorin may play a potential role in PXG and may be used as a novel therapeutic target for glaucoma." (PMID 36611867, 2022).
Hydrocephalus (5 papers, 2008 to 2022). Hydrocephalus is an active distension of the ventricular system of the brain resulting from inadequate passage of CSF from its point of production within the cerebral ventricles to its point of absorption into the systemic circulation. "Our findings highlight the therapeutic potential of decorin to attenuate hydrocephalus-induced changes in astrogliosis, oedema and demyelination, particularly in the caudal periventricular white matter." (PMID 27246837, 2016). "Here we have used kaolin to induce communicating hydrocephalus to help us determine the therapeutic effects of decorin." (PMID 27246837, 2016). "Our recent study supports the key role of transforming growth factor-beta (TGF-β) in communicating hydrocephalus, as decorin, a TGF-β antagonist ameliorated subarachnoid fibrosis and therefore significantly attenuated the enlargement of the ventricular system." (PMID 27246837, 2016). "Our study has also revealed an increase in the AD and RD of the caudal corpus callosum in communicating hydrocephalus, which is additionally preventable by decorin treatment." (PMID 27246837, 2016). "Overall, these findings suggest that decorin has the therapeutic potential to reduce white matter cytopathology in hydrocephalus." (PMID 27246837, 2016). "However, the fact that treatment began before the onset of hydrocephalus and the large number of exclusions from the decorin group makes this an interesting proof-of-principle only." (PMID 26846184, 2016). "Accordingly, communicating hydrocephalus was induced by injecting kaolin into the basal cisterns in 3-week old rats followed immediately by 14 days of continuous intraventricular delivery of either human recombinant decorin (n = 5) or vehicle (n = 6)." (PMID 27246837, 2016). "However, the effectiveness of decorin to prevent cytopathology in hydrocephalus is yet to be examined thoroughly." (PMID 27246837, 2016). "Decorin was detected at about 45 kDa; it was more abundant in the 10 month rat brain than at other ages, but there were no changes associated with hydrocephalus (not shown)." (PMID 18616813, 2008). "Hence, this study aimed to determine whether decorin treatment influences alterations in diffusion tensor imaging parameters and cytopathology in experimental communicating hydrocephalus." (PMID 27246837, 2016). "Therefore, using immunohistochemistry and clinically relevant neuroimaging we investigated whether decorin is able to attenuate damage-related parameters and if cellular changes in communicating hydrocephalus can be quantitatively characterised by DTI using a juvenile rat model of the disorder." (PMID 27246837, 2016).